JUN (Jun proto-oncogene, AP-1 transcription factor subunit)
Diseases named in the same sentence as JUN in open-access papers (continued):
Sharing a sentence is not in itself a finding about the gene and the disease.
melanoma (continued). "JUN and/or AP-1 and TEAD has been shown to induce resistance to vemurafenib (small-molecule inhibitor of BRAF V600E) in cultured patient-derived melanoma cells." (PMID 35883668, 2022). "In human melanoma, HDAC8 was also shown to induce a resistance to BRAF inhibition through targeting c-JUN." (PMID 34064422, 2021). "It is possible that HDAC8 induces PLCB1 through deacetylating/activating c-JUN, as in the BRAF inhibitor-resistant melanoma." (PMID 34064422, 2021). "Some miRs directly target important transcription factors, such as miR-200 regulation of ZEB in epithelial carcinomas, while in melanoma, miR-148 mediated dysregulation of MITF and miR-125b control of JUN have been noted." (PMID 27852308, 2016). "Our data confirm that, in metastatic melanomas, the ERK constitutive signaling activates c-JUN and P-T38-ETS-1, which in turn seem to cooperate towards miR-221/-222 activation." (PMID 21711453, 2011). "For example, in melanoma cells strongly upregulated miR-3689f, miR-6840-5p, miR-4652-5p, miR-4706, and miR-4435 share the target FOSL2, a transcription factor that dimerizes with JUN and binds to AP-1 sites." (PMID 34073664, 2021). "Furthermore, c-JUN expression was found to parallel with SNAI2 expression, and correlated with a mesenchymal gene signature in a panel of melanoma cell lines and a patient cohort." (PMID 27323831, 2016). "We hypothesized that prolonged TNF-α exposure (72 h) steadily increases c-JUN mRNA and protein expression through reduction of MITF and thereby progressively amplifies inflammatory gene programmes in melanoma cells." (PMID 26530832, 2015). "Along the trajectory, the gene signature of cluster 3 in melanoma cells was characterized as the activation of certain functional pathways, including the cell adhesion pathway (VIM), immune response signaling pathway (JUN, EGR1), and melanosome organization signaling pathway (MLANA)." (PMID 38862482, 2024). "JQ1 was characterized by induction of inhibitory relationship linking regulators of inflammation (IFNG, IL17A, TGFB2), melanoma biological behavior (EGFR, WNT3A, TEADs, MRTFB), cell-cell interaction (CD44, CCN2), YAP pathway (LLGL2, NSUN6) and main transcriptional regulators (FOS, JUN, FOXM1)." (PMID 36397155, 2022). "These genes along with their activation values Eq for melanoma (MEL) are, GPNMB (MEL activation = 18.59), UBL3 (MEL activation = 1.39), AP1S2 (MEL activation = 1.28), RAB38 (MEL activation = 0.91), EDNRB (MEL activation = 0.55), JUN (MEL activation = 0.34), and C1orf21 (MEL activation = -0.13)." (PMID 34570764, 2021). "Furthermore, we detect an interaction between monomeric α-tubulin and c-JUN protein, which stabilizes the transcription factor, influences its transport to the nucleus, and subsequently affects c-JUN and thus AP-1 activity in malignant melanoma." (PMID 31744174, 2019). "Furthermore, c-JUN, which might be a potential binding partner for FOSL1 in the AP-1 complex, is highly expressed in most melanoma and is required for tumor transformation." (PMID 20663135, 2010). "Moreover, as reported and confirmed by our small interfering experiments showing c-JUN upregulation in Dsi-ETS-1-transfected melanoma cells (results not shown), c-ETS-1 is able to repress c-JUN, interfering with its strong transcriptional regulation." (PMID 21711453, 2011).
hepatocellular carcinoma (104 papers, 2010 to 2025). A malignant tumor that arises from hepatocytes. "It was found that JUN protein level was significantly modified by O-linked β-N-acetylglucosamine (O-GlcNAcylation), thereby inhibiting ferroptosis in human hepatoma cells such as Bel-7402 and SMMC-7721." (PMID 39171207, 2024). "Previously, it has been demonstrated that in MCF7 breast cancer cells, STAT3 collaborates with FRA1 and c-JUN AP1 components to activate the MMP9 promoter, while in HepG2 hepatoma cells, STAT3 associates with HDAC1 to inhibit IL6-induced CCL2 transcription." (PMID 39274912, 2024). "We enriched the common target genes in the GO pathway and KEGG pathway and found that AKT1, RELA, and JUN are likely to be potential therapeutic targets for hepatocellular carcinoma." (PMID 36874613, 2023). "C-Jun transcriptionally stimulated MYH9 expression to form MYH9/GSK3B/β-catenin/JUN feedback loop regulating CSC properties in hepatocellular carcinoma." (PMID 35242279, 2022). "VEGFA and JUN were identified as the central players in diabetic nephropathy and Alzheimer’s disease whereas, VEGFA was associated with diabetic retinopathy, cardiac autonomic neuropathy, and non-alcoholic fatty liver disease-hepatocellular carcinoma." (PMID 36482897, 2022). "In this context, a report indicated that hsa-miR-1285-3p could directly inhibit the expression of the JUN oncogene in hepatocellular carcinoma." (PMID 36248377, 2022). "In the hepatocellular carcinoma cell line Hepa 1–6, overexpression of JUN together with FOS could enhance the activity of MET, which also seems to be a downstream target of PA1." (PMID 35379345, 2022). "In addition, a high expression level of JUN was indifferently retained in the medium-differentiated hepatoma and para-carcinoma tissues." (PMID 32273945, 2020). "For instance, overexpression of EYA4 suppresses the c-JUN-mediated angiogenesis and metastasis of hepatocellular carcinoma (HCC) in nude mice." (PMID 36741265, 2023). "In Hepatocellular cancer (HCC)/liver cancer (LiC) cells, the integrin β1/α5/JNK/c-JUN signaling pathway participates in higher matrix stiffness, which is induced by LOXL2 (lysyl oxidase homolog 2)." (PMID 37384249, 2023). "At the same time, some studies have shown that JUN and FOS are closely related to the formation of hepatocellular carcinoma." (PMID 36380355, 2022). "We found that STAT6 mediates two modules, while TFs such as JUN, AES, and AR mediate a module that affects the development and progression of hepatocellular carcinoma." (PMID 34651050, 2021). "MiR-1204 facilitates the development of hepatocellular carcinoma by stimulating MAPK and c-JUN/AP1 pathway via targeting ZNF418." (PMID 32280303, 2020). "In conclusions, CCL3, CCL3L1, JUN, IL8, and IL1B have the potential to be considered as candidates for future molecular diagnosis of the hepatic carcinoma with metastasis." (PMID 28427195, 2017). "CCL3, CCL3L1, JUN, IL8, and IL1B were identified in inflammation mediated by chemokine and cytokine signaling pathway (P00031) in the hepatic carcinoma samples with metastasis, and subsequently confirmed by quantitative real-time polymerase chain reaction." (PMID 28427195, 2017). "Among those genes found to be down-regulated following ATIII treatment were JUN and MYC, which are known to be important factors in the pathogenesis of HCV-related hepatocellular carcinoma." (PMID 23031791, 2012). "In human hepatoma cells, GSH inhibited the egg product-induced activation of ERK, c-JUN, and STAT3." (PMID 36590323, 2022). "Next, analysis of Wnt/β-catenin signaling components revealed that mRNA expression levels of Wnt5A, CTNNB1P1, DVL1, SMAD4, and JUN were detected in well-differentiated hepatoma but not in their para-carcinoma tissues." (PMID 32273945, 2020).
hepatocellular carcinoma (continued). "Besides, in this study, we also found the up-regulated JUN and IL1B in the samples of hepatic carcinoma with metastases." (PMID 28427195, 2017). "The results showed that wogonin and baicalein, the main chemical components of SB, could inhibit the viability and proliferation of hepatocellular carcinoma cells, promote apoptosis through the mitochondrial apoptotic pathway, and effectively act on AKT1, RELA, and JUN targets." (PMID 36874613, 2023). "Finally, in order to further validate these 5 DEGs, RT-qPCR were performed and the result was the same with that of RNA-seq, demonstrating that CCL3, CCL3L1, JUN, IL8, and IL1B were reliable and available to be used as the candidates for hepatic carcinoma with metastasis." (PMID 28427195, 2017). "Bioinformatics analysis has identified PI3K, transcription factor AP-1 (JUN), and signal transducer and activator of transcription 3 (STAT3) as predictive targets through which SW exerts its anti-tumor effects in hepatocellular carcinoma (HCC)." (PMID 40801607, 2025). "Furthermore, FAM83A is upregulated in hepatocellular carcinoma and correlates with poor progression-free survival, and induces migration, invasion and metastasis of the tumor cells by activating EMT signaling and forming a FAM83A/PI3K/AKT/c-JUN positive-feedback loop." (PMID 38914812, 2024). "Unlike the JUN gene, which is known to regulate myeloid differentiation, the KLF6 gene is a known tumor suppressor for prostate, colorectal, lung, ovary, gliomas, head and neck, and hepatocellular cancer." (PMID 37298367, 2023).
lung cancer (99 papers, 2008 to 2026). A malignant neoplasm involving the lung. "JUN was reported to associate with the acquisition of anchorage independence of lung cancer cell lines, which might contribute to the process of lung carcinogenesis." (PMID 32595734, 2020). "Its ten hub genes were extracted and confirmed in the literature; seven of them (UBC, SRC, SP1, MYC, STAT3, RB1, and MAPK1) were verified to be associated with lung cancer, while the remaining three genes, JUN, NR3C1, and GRB2, were potentially new candidate lung adenocarcinoma-related genes." (PMID 26402252, 2015). "In our study, we studied that the PI3K-AKT pathway plays a key role in cyclomorusin-induced apoptosis in lung cancer cells, but the role of JUN in cyclomorusin-induced apoptosis in lung cancer cells need to be further explored." (PMID 40510163, 2025). "Lung cancer cell lines displayed heightened sensitivity to FOSL1 depletion compared to JUN knockout." (PMID 40414926, 2025). "The regulation of Smad target gene expression by m6A methylation is also involved in modulating JUN (encoding c-Jun) and JUNB (encoding JunB) expression during EMT in lung cancer cells." (PMID 38569937, 2024). "We identified a new valuable gene, JUN, and described the unique pattern of cellular microenvironment that determines response to PD-1 blockade therapy on lung cancer patient." (PMID 38874497, 2024). "A larger cohort from KMplot database of lung cancer was enrolled for survival analysis which exhibited high expression of JUN resulted a better prognosis (P=0.00023)." (PMID 38874497, 2024). "The expression of ERCC1 protein is a main predictor of the benefit of cisplatin-based chemotherapy in lung cancer, and its gene contains AP-1 sites bound by the transcription factors JUN and ATF2." (PMID 37686122, 2023). "Some of the altered genes are already serving as treatment targets, e.g., PDL-1, ITBG2, TGFB1, and c-JUN, in many cancer types, including lung cancer." (PMID 37568601, 2023). "Taken together, we concluded that the m6A_1 and m6A_3 sites of JUN 3′UTR were responsible for METTL3-mediated regulation of JUN protein expression in A549 lung cancer cells." (PMID 36183833, 2022). "Among them, TNF had the greatest degree in the HCT-major hub genes-disease network, while IL-6, JUN, EGFR, and MYC were shown to associate with the survival of lung cancer patients." (PMID 32595734, 2020). "We found that doses of tetracenomycin X elevated the phosphorylation levels of the p38 and c-JUN proteins in the five lung cancer cells, and tetracenomycin X (5 μmol/L) also active the p38 and c-JUN proteins in 4–16 h in the A549 and H460 cells." (PMID 30669360, 2019). "Our results show that tetracenomycin X only activates the phosphorylation levels of p38 and c-JUN proteins in lung cancer cells, which leads to the downregulation of cyclin D1." (PMID 30669360, 2019). "Additionally, NR0B1 has been implicated in modulating ferroptosis resistance through activation of the c-JUN/NRF2-CBS signaling axis in lung cancer cells, suggesting a complex interplay between NR0B1 and multiple transcriptional regulators." (PMID 40864301, 2025). "In addition, lung cancer samples with KRAS mutations showed higher mRNA levels of MT-CO2, c-JUN, or GLS1." (PMID 39747079, 2025). "The IHC experiment was performed to further identify the JUN expression in lung cancer tissues." (PMID 38874497, 2024).
lung cancer (continued). "To further demonstrate that JUN is associated with PD-1 signaling pathway activation (search in KEGG database), we extracted the RNA sequencing data of lung cancer patients with LUAD from the TCGA database to analyze the correlation between JUN and PD-1 blockade treatment response." (PMID 38874497, 2024). "For example, AGR3 has been shown to facilitate the stemness of colorectal cancer by regulating Wnt/β-catenin signaling; STC2 has been shown to be involved in resistance to treatment with EGFR tyrosine kinase inhibitors and to promote the progression of lung cancer by regulating JUN/AXL signaling." (PMID 33680908, 2020). "Though the impact of JUN on the survival of lung cancers remains vague, a study on lung adenocarcinoma cell line (HCC827) showed that increased JUN expression was associated with gefitinib resistance in NSCLC and might lead to a poor prognosis." (PMID 32595734, 2020). "IL-6, JUN, EGFR, and MYC were shown to associate with the survival of lung cancer patients." (PMID 32595734, 2020). "TNF, EGFR, MYC, IL-6, and JUN were identified as major hub genes of HCT on lung cancer." (PMID 32595734, 2020). "Also, the ERK1 checkpoint in the downstream of EGFR and IGF1R is inactivated by miR-140-3p, leading to a reduction of active AP-1 proteins including FOS and c-JUN, thus modulate invasion and transformation of lung cancer cells." (PMID 30559931, 2018). "Drug response assays showed that gefitinib suppressed PC-9 cell proliferation equally well in the 3D lung cancer model as in 2D culture dishes, albeit over a smaller volume of cells, suggesting that fluctuations in gefitinib resistance genes such as JUN may affect drug sensitivity." (PMID 37434755, 2023). "JUN is altered in 0.87% of all cancers due to missense, nonsense mutations, silent and frameshift insertions, and deletions are observed in cancers such as intestinal cancer, lung cancer, and skin cancer." (PMID 36982429, 2023). "Therefore, we investigated the functional role of JUN in lung cancer." (PMID 34236045, 2021). "Bioinformatic analysis via the TCGA database revealed that the expression levels of JUN and CXCL8 are higher in stage IV lung cancer, suggesting a potential positive correlation between their expression and disease progression." (PMID 39990658, 2025). "For example, in pancreatic and lung cancer, it has been reported that oncogenic KRAS mutants stimulate the transcription of NRF2 via JUN and MYC." (PMID 37373496, 2023). "In this study, we found that knockdown of JUN and JUNB affected the expression of epithelial and mesenchymal marker genes during TGF-β-dependent EMT of A549 and LC2/ad lung cancer cells." (PMID 36183833, 2022). "In summary, we demonstrated the different modes of m6A regulation for JUN and JUNB TFs, which play an integral role in the EMT-inducing gene regulation during TGF-β-dependent EMT of lung cancer cell lines." (PMID 36183833, 2022). "Overall, our results demonstrated that both common and individual functions of JUN and JUNB TFs were important in the transcriptional regulation during EMT of lung cancer cells." (PMID 36183833, 2022). "Previously, CDDO-Me and CDDO-Im were shown to increase the expression of JUN (1 μM; H157 cells (2–8 h)) and FOS (0.2 μM (6 h)) in human lung cancer cells and HUVEC, respectively." (PMID 31523389, 2019). "For instance, EGR1, JUN, PPARG, and RELA may have a beneficial effect in lung cancer, related to inhibition of tumor proliferation and metastasis, induction of apoptosis, and sensitization for chemotherapeutic drugs." (PMID 36969247, 2023).
lung cancer (continued). "We have so far demonstrated that the m6A regulation of JUN and JUNB by METTL3 plays a critical role in the expression levels of them, thereby affecting the EMT-inducing gene expression program of A549 and LC2/ad lung cancer cells." (PMID 36183833, 2022). "The m6A-modified JUN mRNA was increased by TGF-β treatment in A549 and LC2/ad lung cancer cells." (PMID 36183833, 2022). "Stabilization of these onco-proteins during CPPD exposure indeed depends on USP28, as the lung cancer cell line SK-MES1 (SCC), which is mutant for USP28 and expresses low levels thereof, showed some degree of c-JUN or c-MYC destabilization after CPPD treatment." (PMID 34611298, 2022). "However, three hub genes JUN, FGF2, CCND1 and IL6 expressed fewer mRNAs in lung cancer tissues than normal lung tissues." (PMID 32210363, 2020). "And the interaction of ITGB4 promoter with some transcription factors in other disease is also reported, such as KLF4 in glioma 21, RUNX1 in myeloid leukemia 22, ZEB1 in prostate cancer 23, TP73 in lung cancer 24, GLI1 in ovarian cancer 25, and JUN in pancreatic cancer." (PMID 31602273, 2019). "Besides, NT157 decreased expression of oncogenes BCL2, CCND1, MYB, and MYC and increased genes related to cellular stress and apoptosis, JUN, BBC3, CDKN1A, CDKN1B, FOS, and EGR1 (p < 0.05), favoring a tumor-suppressive cell signaling network in the context of lung cancer." (PMID 36224313, 2022). "Our attempts to test for the binding of endogenous c-Jun to the BLIMP1 promoter in A549 lung cancer cells cultured in growth medium supplemented with 10% FBS were unsuccessful as no amplification of either the BLIMP1 or positive control JUN TRE sites was detected in ChIP analyses (data not shown)." (PMID 22438909, 2012). "To validate the involvement of YTHDF3 and IGF2BP1 in the regulation of JUN and JUNB expression, we confirmed the knockdown effects in protein and mRNA expression in A549 and LC2/ad lung cancer cells with or without TGF-β treatment." (PMID 36183833, 2022). "In this study, we discovered the m6A RNA modification–dependent regulation of JUN and JUNB TFs, which plays an essential and nonredundant role in gene expression program during TGF-β-induced EMT of A549 and LC2/ad lung cancer cells." (PMID 36183833, 2022). "Quantitative RT–PCR (QRT–PCR) revealed that the expressions of JUN and JUNB but not of JUND mRNA were increased by TGF-β in A549 and LC2/ad lung cancer cell lines." (PMID 36183833, 2022).